BDNF (brain derived neurotrophic factor)
Diseases named in the same sentence as BDNF in open-access papers (continued):
Sharing a sentence is not in itself a finding about the gene and the disease.
depression (continued). "Recently, EF-2001 was shown to prevent OBX-induced depression-like behaviors through the regulation of prefrontal cortical myelination via the enhancement of CREB/BDNF and NF-κB p65/LIF/STAT3 pathways." (PMID 37139495, 2023). "Research examining postmortem brain tissue from individuals diagnosed with bipolar disorder (BD) and major depressive disorder (MDD) revealed a decrease in BDNF levels in the hippocampus and prefrontal cortex, areas linked to memory processing." (PMID 37763162, 2023). "Neither menstrual cycle-dependent changes nor relationships with neural processing and/or hormones were detected for depression, anxiety, premenstrual syndrome and the brain-derived neurotrophic factor or the insulin-like growth factor." (PMID 37509620, 2023). "Deficits in BDNF signaling are associated with the pathogenesis of various neurological and psychiatric disorders, including Alzheimer’s disease (AD) and depression, whereas BDNF administration attenuates amyloid-β peptide-induced memory deficits." (PMID 37626746, 2023). "Evidence suggests that BDNF levels are lower in individuals with depression, and antidepressant medications can increase BDNF levels." (PMID 37845289, 2023). "Serum BDNF, NT-3, and 5-HT levels substantially correlate with anxiety and depression in MHD patients." (PMID 37750080, 2023). "BDNF is one of the most common neurotrophic factors in the central nervous system that suppresses depression-like behaviors." (PMID 38105928, 2023). "CREB is a transcription factor that regulates the expression of several genes involved in neuroplasticity (including BDNF) and cell survival and has also been widely involved in the pathophysiology of depression and in AD treatments." (PMID 37047730, 2023). "A recent study revealed that, after 100 days of selective serotonin reuptake inhibitor treatment, methylation of promoter CpG sites of BDNF was significantly decreased, reducing depression scores after this treatment." (PMID 37631295, 2023). "The aim of the present study was to determine the effects of hesperidin on depression, serum brain‐derived neurotrophic factor (BDNF), and serum cortisol levels in post‐coronary artery bypass graft (CABG) patients." (PMID 38107143, 2023). "Lower ghrelin levels are thought to promote a reduction in BDNF levels and cognitive impairment in depression via the inhibition of the cAMP-signaling pathway in depressed male mice." (PMID 37764744, 2023). "A reduction in BDNF, a bridge between atherosclerotic cardiovascular disease and depression, is predictive of long-term mortality." (PMID 38275390, 2023). "It is thus not surprising that the focus of the pharmacological study on phytochemicals for the treatment of depression has been targeting neurotrophic factors, among which BDNF, GDNF, VEGF, and NGF are the most relevant neurotrophins." (PMID 37089920, 2023). "Whole-body vibration also increases the expression of FNDC5 and BDNF, which are beneficial proteins for the body that increase muscle strength and protect the nervous system, and play a positive role in treating depression." (PMID 37511879, 2023). "In these experiments, chronic stress and depression led to a reduction in BDNF levels, an increase in cell death, a decrease in the growth of new neurons in the hippocampus, and a decrease in BDNF expression in other regions of the brain." (PMID 37631295, 2023). "The pro-neurogenic properties of BDNF are particularly relevant in the context of depression, since impairments in neurogenesis have been correlated with behavioral deficits observed in animal models of depression." (PMID 38069198, 2023).
depression (continued). "Studies support the link between oxidative stress and neurogenesis and synaptic plasticity impairments in depression, mainly by connecting them with BDNF." (PMID 36830028, 2023). "A variety of studies have implicated impaired BDNF/TrkB signaling and Erk1/2/MAPK pathway in the pathogenesis and treatment of depression." (PMID 36818650, 2023). "The role of BDNF in the development of depression in patients after cardiovascular events other than stroke should be investigated, including the assessment of BDNF alteration in response to cardiovascular injury." (PMID 37895349, 2023). "Here, we show current evidence showing a close relationship between the downregulation of BDNF/TrkB system and the depression models after the glucocorticoid stress." (PMID 37781095, 2023). "Stress can lower BDNF levels in the brain, resulting in hippocampal and prefrontal cortex atrophy, cell death, and severe depression." (PMID 37780709, 2023). "The study investigated the levels of adipokines and BDNF that are important in the neuroinflammatory theory of depression." (PMID 37891727, 2023). "Considerable clinical evidence over subsequent decades has demonstrated BDNF plays an important role in depression." (PMID 37881439, 2023). "On the basis of these findings, we believe that the low TrkB.T1 level is an adaptation to an initially low level of BDNF seen in this model of depression." (PMID 37761014, 2023). "The PI3K/Akt signalling pathway is the primary downstream signalling pathway in BDNF/TrkB signalling, regulating neuronal cell growth and survival in the hippocampus and mediating stress-induced depression and antidepressant effects." (PMID 36737776, 2023). "Previous interventional studies have revealed that probiotics can restore the levels of pro-BDNF and BDNF in various brain regions which are related to the development of depression-like behavioral phenotypes." (PMID 37139495, 2023). "Peripheral administration of LPS, used as an inflammatory model of depression, also results in decreased levels of BDNF in the brain, reduced expression of BDNF mRNA, and reduced BDNF protein levels in the rat hippocampus." (PMID 37047638, 2023). "According to the biochemical analysis, improvement of depression symptoms was associated with reduced level of CRP, increased production of BDNF, and incremented access brain to serotonin." (PMID 37537722, 2023). "Results in rodent models indicate that a single dose of ketamine induces robust markers of neuroplasticity in depression-relevant brain regions, including increased BDNF release and the stimulation of mTOR signaling in the PFC." (PMID 37160885, 2023). "In line with this argument, experimental models have demonstrated that inhibition of P2X7R alleviates depression via BDNF activation." (PMID 35821455, 2023). "In a study with patients with major depressive disorder it was found that BDNF levels were low and proBDNF levels were high in the serum and exosomes of patients compared to controls, and BDNF levels increased, and proBDNF levels decreased with treatment." (PMID 37464177, 2023). "Another report showed alterations in the expression of BDNF and its precursor BDNF in the postmortem brain of depressed patients, suggesting that this protein can potentially serve as a biomarker for depression." (PMID 37400661, 2023). "The interplay of oxidative stress, HPA axis imbalance, and serotonergic pathways with BDNF is also an important topic of research, playing a significant role in the development and progression of depression and other neuropsychiatric disorders." (PMID 37631295, 2023). "BDNF plays a crucial role in the regulation of neuronal cell growth, differentiation, and the pathophysiology of several mental disorders such as depression." (PMID 37396946, 2023). "The aim of the present study was, therefore, to determine the effects of hesperidin on the severity of depression, serum BDNF, and cortisol levels in post‐CABG patients." (PMID 38107143, 2023).
depression (continued). "In fact, several anxiety- and depression-related indicators such as immobility time in the forced swimming test (FST), serum corticosterone level, and hippocampal BDNF concentration were significantly associated with XO activity in the cerebral cortex." (PMID 37139495, 2023). "BDNF is regarded to be negatively related with the neuropsychiatric disorders such as cognitive malfunction, anxiety and depression." (PMID 37407491, 2023). "The aim of the present study was, therefore, to determine the effects of hesperidin on depression, serum brain‐derived neurotrophic factor (BDNF), and serum cortisol levels in post‐coronary artery bypass graft (CABG) patients." (PMID 38107143, 2023). "BDNF can be used as a biomarker of depression or as a measure of antidepressant efficacy predictors." (PMID 37108261, 2023). "When such EVs were injected into lipopolysaccharide (LPS)-challenged mice (a depression-like model), they had beneficial effects on the increased immobility time, anhedonia-like behavior, decreased BDNF expression, and microglia activation." (PMID 36302978, 2023). "Studies have shown that depression scores and biomarkers such as event-related potential (P300) and brain-derived neurotrophic factor (BDNF) decrease and improve after yoga therapy." (PMID 37711938, 2023). "Consistently, we found that EE reversed the MSD-induced downregulation of the BDNF/TrkB signaling pathway to improve depression and cognitive impairment." (PMID 37168717, 2023). "Recent systematic reviews and meta-analyses have concluded that Lactobacillus and Bifidobacterium probiotics have the most significant effect on the augmentation of BDNF levels in patients with depression." (PMID 36986112, 2023). "BDNF and its receptor TrkB are crucially involved in depression aetiology and antidepressant's therapeutic mechanisms." (PMID 37799103, 2023). "We observed that fluoxetine treatment improved the cefaclor-induced reduction of serotonin and BDNF levels as well as the expression of pro-inflammatory cytokines, resulting in decrease anxiety- and depression-like behaviors in mice." (PMID 37726354, 2023). "Some evidence even suggests that WBC has benefits on mental health (depression, anxiety disorders) and cognitive functions in both adults and older adults, due to increased circulating BDNF levels." (PMID 37770960, 2023). "Being a player in several diseases, the connection of the BDNF signaling pathway with major depressive disorder is widely studied, being very important in advancing the understanding and treatment of this disorder." (PMID 37631295, 2023). "Only one study examined the role of possible altered serum BDNF levels in the development of depression in patients with coronary heart disease." (PMID 37895349, 2023). "Preclinical research studies have found that BDNF regulates BDNF expression and has antidepressant-like effects in animal studies, implying a function for BDNF in depression." (PMID 37228982, 2023). "Various exercise-induced factors released into the bloodstream from muscle, liver, and bone, have been shown to cross the blood-brain barrier (BBB) enhancing brain-derived neurotrophic factor (BDNF) signaling, and alleviating the symptoms of depression." (PMID 37398548, 2023). "Therefore, we proposed a hypothesis that the pathophysiological mechanism of depression and impulsive behaviors in drug-naïve patients with first-episode schizophrenia might be associated with BDNF, PI3K, AKT, and CREB in the corresponding cellular signaling pathways." (PMID 37013544, 2023). "In the BDNF gene, the SNP, which is the substitution from valine (Val) to methionine (Met) in the functional coding region at codon 66 (BDNF Val66Met), has received the most attention in mental disorders, including depression." (PMID 36517640, 2023).
depression (continued). "In mouse and postmortem sample patients, downregulation of BDNF was related to depression in various brain regions, including the anterior cingulate cortex, caudal brainstem, ventral prefrontal cortex, and hippocampus." (PMID 35821455, 2023). "This strategy was further developed in the present study to investigate SERT, BDNF, and synaptic biomarkers of depression in FB-Es." (PMID 38201206, 2023). "Being implicated in the pathophysiology of disorders such as Alzheimer’s disease, Parkinson’s disease, and major depression disorder, BDNF is an active area of investigation in neuroscience and related fields." (PMID 37631295, 2023). "Acupuncture at Baihui (GV20) and DU29 effectively counteract the chronic stress-induced down-regulation of BDNF mRNA and protein expression in the frontal cortex and hippocampus of rat models of depression." (PMID 37732301, 2023). "Our findings indicate that the expression of BDNF was hindered and that the levels of synaptic plasticity-related proteins were downregulated, resulting in the manifestation of depression-like behaviour." (PMID 37735410, 2023). "Accordingly, decreased levels of BDNF, accompanied by low levels of adult neurogenesis, occurs in brains of older adults with impaired cognitive function and in those of patients with major depression disorder." (PMID 36834953, 2023). "Intriguingly, when subjected to repetitive transcranial magnetic stimulation (rTMS), patients suffering from depression manifest symptom improvement, along with an inverse correlation between BDNF and neopterin." (PMID 36214902, 2023). "A reduction in the brain-derived neurotrophic factor (BDNF) level in the brain causes depression, whereas an increase in its level has therapeutic benefits against depression." (PMID 38082356, 2023). "The hippocampus, which is sensitive to altered cortisol, serotonin, and brain-derived neurotrophic factor (BDNF) levels, is also affected by both depression and AD." (PMID 37720905, 2023). "Our results showed that BDNF rs6265, PTEN rs12569998, and SYN1 rs1142636 SNP were associated with treatment-resistant depression (TRD)." (PMID 37047730, 2023). "KF is also reported to reverse the oxidative stress-induced-decrease of hippocampal BDNF and cAMP Response Element Binding Protein expression, leading to hippocampal neurogenesis and ameliorating depression and cognitive deficits." (PMID 37539232, 2023). "A decrease in BDNF mRNA levels is observed in the hippocampus of chronically stressed rats and patients with depression." (PMID 37492530, 2023). "The level of brain-derived neurotrophic factor (BDNF) in peripheral serum is closely related to the severity of depression." (PMID 37065890, 2023). "Recent studies have suggested that the dysregulation of BDNF contributes to the pathogenesis of several major diseases and disorders, such as Huntington's disease, Alzheimer's disease, and depression, especially mediated by epigenetic processes." (PMID 37008217, 2023). "It has been demonstrated that decreased levels of BDNF activity in the hippocampus are strictly related to depression." (PMID 37109038, 2023). "It is of interest to note that several metabolites posited in this paper, that are important in explaining the link between the gut microbiome, DNA methylation and depression, have already been identified as relevant to the DNA methylation of BDNF." (PMID 37317308, 2023). "Subgroup analysis revealed that DM patients suffering from depression exhibit lower serum levels of BDNF comparing with controls." (PMID 36787304, 2023). "Given the presence of readily measurable levels of BDNF in human serum, a very large number of studies have attempted to correlate the levels of BDNF with depression." (PMID 37470055, 2023). "Supporting this, decreased BDNF levels in the serum have been observed in patients with mood disorders under excessive stress and depression." (PMID 37242280, 2023).
depression (continued). "Supplementation with tryptophan, the precursor of serotonin synthesis, also ameliorated stress-induced depression-like behavior in mice by the improvement of neuroinflammation, mitochondrial energy metabolism, and increased expression of BDNF." (PMID 37631295, 2023). "Crocus sativus L. (Saffron), as one of the most clinically effective herbal extracts, has shown antidepressant effects in various experimental depression models by modulating the BDNF, cyclic AMP response element binding protein (CREB), and VGF pathways." (PMID 37047914, 2023). "Meta-analysis of three studies showed significantly lower levels of serum BDNF in DM patients with depression (n = 152) compared to the controls (n = 300) (SMD = -1.69 [-2.41, -0.98], P<0.001)." (PMID 36787304, 2023). "It has been observed that patients with psychiatric disorders and especially with depression often demonstrate reduced BDNF concentrations in their blood and brain, while antidepressant treatment can increase BDNF levels." (PMID 36794673, 2023). "For example, rodents subjected to persistent stress were shown to exhibit decreased BDNF expression levels and hippocampal atrophy—an alteration that has also been evinced in major depressive disorder in humans." (PMID 36766691, 2023). "In contrast, an increased risk of developing MDD for homozygote genotype TT (Met/Met) and the possible role of BDNF in the pathogenesis of major depression was observed in studies from Asia." (PMID 37626739, 2023). "One possible biological explanation is that resistance exercise, being high-frequency and short-duration, triggers an increase in serum BDNF, promoting central neurotransmitter release and thereby effectively improving depression." (PMID 37333923, 2023). "This suggests that inflammation-activated neuronal C/EBPβ can contribute to HFD-induced depression by decreasing BDNF expression." (PMID 37387537, 2023). "Direct comparisons across distinct mood states demonstrated that the reduction in peripheral BDNF levels was comparable in mania and depression and that both were equally reduced compared to euthymia." (PMID 37592949, 2023). "More research is needed to elucidate the pathophysiological link between BDNF dysregulation and depression." (PMID 37242525, 2023). "BDNF has been identified as a potential circulating biomarker for schizophrenia or depression and neurodegenerative diseases." (PMID 37109038, 2023). "Research has proven that the serum levels of BDNF were reduced in patients diagnosed with major depressive disorder, which indicated that BDNF played a critical role in the pathophysiology of depression." (PMID 36767702, 2023). "For depression, decreased serum BDNF levels and decreased neuroplasticity are important pathophysiological mechanisms." (PMID 37469252, 2023). "For instance, a study performed on 84 adolescent patients with depression revealed significantly decreased levels of BDNF compared to the healthy control (n = 64) and a significant negative correlation between BDNF level and clinical symptoms severity." (PMID 34590201, 2023). "First, pro-inflammatory cytokines such as IL-6 and TNF impair the expression of BDNF, leading to the onset of depression." (PMID 36978923, 2023). "Postmortem human studies of individuals with depression and/or who have died by suicide show reduced BDNF protein levels in the hippocampus and other brain regions, contrary to individuals receiving antidepressant treatment." (PMID 37398548, 2023). "The molecular and cellular mechanisms of ginseng and its active ingredients regulate monoamine neurotransmitters, upregulate the expression of BDNF and have anti-inflammatory effects, which are of great importance in treating depression." (PMID 37836833, 2023). "Reduced BDNF blood levels have been reported in individuals with schizophrenia, bipolar disorder, and depression." (PMID 37763162, 2023).